LAX1 (lymphocyte transmembrane adaptor 1)
Description:
Negatively regulates TCR (T-cell antigen receptor)-mediated signaling in T-cells and BCR (B-cell antigen receptor)-mediated signaling in B-cells.
Synonyms: LAX; FLJ20340
Tractability: Antibody: UniProt places it where antibodies can reach, with high confidence; its Gene Ontology location is reachable by antibodies, with high confidence; UniProt predicts a signal peptide or a membrane-spanning region; the Human Protein Atlas places it where antibodies can reach. PROTAC: ubiquitination databases record sites on it.
Gene: Protein-coding gene on chromosome 1 (203,765,177 to 203,778,175, forward strand). Ensembl gene ENSG00000122188.
Subcellular location: Cell membrane
Subcellular location (Human Protein Atlas): Cytosol; Plasma membrane; Golgi apparatus
Gene Ontology:
Molecular function: protein binding; protein kinase binding; SH2 domain binding
Biological process: B cell activation; immune response; intracellular signal transduction; negative regulation of MAPK cascade; negative regulation of T cell activation; antigen receptor-mediated signaling pathway; lymphocyte activation; regulation of lymphocyte activation
Cellular component: cytosol; Golgi apparatus; membrane; membrane raft; plasma membrane
Genetic constraint (gnomAD): Loss-of-function variants: 11 observed, 14.33 expected, observed/expected ratio (o/e) 0.77, 90% interval 0.48 to 1.27. The upper end of that interval is the gene's LOEUF score, 1.27, which puts it in group 5 of 6, group 1 being the genes least tolerant of losing a copy. Missense variants: 457 observed, 501.25 expected, observed/expected ratio (o/e) 0.91, 90% interval 0.84 to 0.99. Synonymous variants: 162 observed, 187.8 expected, observed/expected ratio (o/e) 0.86, 90% interval 0.76 to 0.98.
Homologues: Orthologues: chimpanzee LAX1 (99% identical), macaque LAX1 (94% identical), pig LAX1 (63% identical), guinea pig LAX1 (62% identical), dog LAX1 (62% identical), mouse Lax1 (51% identical), rat Lax1 (51% identical).
Diseases named in the same sentence as LAX1 in open-access papers:
LAX1 is named in the same sentence as 21 diseases in open-access papers, as found by Europe PMC text mining. Sharing a sentence is not in itself a finding about the gene and the disease. The quoted sentences say what the papers report.
breast carcinoma (2 papers, 2022). "Another report revealed that hypermethylation of genes (LAX1, SIT1, and UBASH3A) leads to enhanced anti-tumor T-cell responses in breast cancer." (PMID 35517856, 2022).
periodontitis (2 papers, 2022 to 2023). An acute or chronic inflammatory process that affects the tissues that surround and support the teeth. "LAX1 is associated with BCR signaling, which plays an important role in chronic lymphocytic leukemia pathogenesis, and its expression is highly correlated with B-cell infiltration in periodontitis." (PMID 38203530, 2023).
asthma (1 paper, 2023). "DMR analysis implicated genes with previously reported links to schizophrenia (LAX1), skin disorders (PSORS1C, LTB4R), and airway inflammation including asthma (LTB4R), present only at birth in the higher latitudes (≥ 50°N)." (PMID 37697338, 2023).
breast tumor (1 paper, 2013). "GRB2 interaction with LAT and LAX1 observed in breast tumor cells may be an indirect interaction through PLCG1, VAV or PIK3R1." (PMID 23826330, 2013).
cerebral malaria (1 paper, 2025). A sequestration of Plasmodium falciparum in the brain, which can cause coma and/or seizures. "We observed that cerebral malaria was associated with significantly reducing LAX1 expression (p = 0.025, 1.85-fold decrease)." (PMID 40441141, 2025). "To assess whether LAX1 expression might be involved in susceptibility to SM, we re-analyzed previously published expression data by comparing the transcriptome of peripheral blood mononuclear cells (PBMCs) from children with cerebral malaria (one form of SM) and uncomplicated malaria." (PMID 40441141, 2025). "LAX1 deregulation and disrupted Ca2+ signaling may drive CD8+ T cell hyperactivation, contributing to SM and particularly cerebral malaria." (PMID 40441141, 2025).
glioma (1 paper, 2018). A benign or malignant brain and spinal cord tumor that arises from glial cells (astrocytes, oligodendrocytes, ependymal cells). "Low level of ERβ reduces the inhibition of invasion of glioma cells influenced by high level of LAX1 expression, leading to an increase in the invasion ability of glioma cells." (PMID 30345080, 2018).
malaria (1 paper, 2025). Malaria is a serious and sometimes fatal disease caused by a parasite that commonly infects a certain type of mosquito which feeds on humans. "Particularly, high accessibility was observed in CD4+ T at the malaria-associated regulatory region and the LAX1 promoter." (PMID 40441141, 2025). "H3K27Ac profiles from Roadmap data, revealed active regulatory elements at the ATP2B4 Epromoter, containing malaria-associated SNPs and the LAX1 promoter in CD4+ T cells." (PMID 40441141, 2025). "Furthermore, our findings revealed an epistatic interaction between ESpromoter SNPs and rs11240391, impacting severe malaria susceptibility by further reducing LAX1 expression." (PMID 40441141, 2025).
mantle cell lymphoma (1 paper, 2013). Mantle cell lymphoma is a rare form of malignant non-Hodgkin lymphoma affecting B lymphocytes in the lymph nodes in a region called the ``mantle zone''. "Parallel to observations in mantle cell lymphoma (MCL) tyrosine phosphoproteome analysis, we see active novel phospho-motifs on several negative regulators of immune signals (LAX1, SHIP1pY556; PILRApY246; IL1RL1pY99 and TNFL6pY258)." (PMID 23826330, 2013).
melanoma (1 paper, 2023). A malignant, usually aggressive tumor composed of atypical, neoplastic melanocytes. "A strong association between the expressions of PKHD1L1 and LAX1 was also confirmed using the Mixed Melanoma-Kunz-80 dataset with the R2 database (R = 0.412, p = 1.0 × 10−4)." (PMID 38203530, 2023).
schizophrenia (1 paper, 2023). A major psychotic disorder characterized by abnormalities in the perception or expression of reality. "Interestingly, DNAm of cg12022621, mapped to the LAX1 gene (Lymphocyte Transmembrane Adaptor 1), has been shown to be associated with severity of certain symptoms of schizophrenia (SZ) in a case–control study." (PMID 37697338, 2023).
infection (2 papers, 2021 to 2022). The state of being infected such as from the introduction of a foreign agent such as serum, vaccine, antigenic substance or organism. "The genes related to the auxin signaling pathway, e.g., LAX1 (LIKE-AUXIN1), LAX2, LAX3, IAA2 (auxin-responsive gene), IAA27, and IAA31, were constant at QS while downregulated at NS after the infection by each strain." (PMID 35251071, 2022).
LAX1 also shares sentences with these, for which no sentence is quoted: tumor (3 papers); autoimmune disease (1); bacterial infections (1); chronic lymphocytic leukemia (1); major depressive disorder (1); Pancreatic Cancer (1); psoriasis (1); Sepsis (1); skin disorder (1); viral infections (1).